ENSG00000248751 (novel protein)
Gene: Protein-coding gene on chromosome 22 (30,285,238 to 30,299,482, reverse strand). Ensembl gene ENSG00000248751.
Genetic constraint (gnomAD): Loss-of-function variants: 34 observed, 60.29 expected, observed/expected ratio (o/e) 0.56, 90% interval 0.43 to 0.75. Missense variants: 518 observed, 662.73 expected, observed/expected ratio (o/e) 0.78, 90% interval 0.73 to 0.84. Synonymous variants: 264 observed, 277.09 expected, observed/expected ratio (o/e) 0.95, 90% interval 0.86 to 1.05.